DNAI1 (dynein axonemal intermediate chain 1)
Description:
Component of dynein, a family of motor proteins essential for movement along microtubules (By similarity). Required for structural and functional integrity of cilia (By similarity). Part of the dynein complex of respiratory cilia.
Synonyms: DIC1; PCD; CILD1; oda6; ICS1
Tractability: Small molecule: a structure with a bound ligand is known. Antibody: its Gene Ontology location is reachable by antibodies, with medium confidence.
Gene: Protein-coding gene on chromosome 9 (34,457,414 to 34,520,988, forward strand). Ensembl gene ENSG00000122735.
Subcellular location: Dynein axonemal particle; Cytoplasm, cytoskeleton, cilium axoneme; Cell projection, cilium, flagellum; Cytoplasm, cytoskeleton
Subcellular location (Human Protein Atlas): End piece; Mid piece; Primary cilium; Principal piece; Vesicles
Gene Ontology:
Molecular function: protein binding; cytoskeletal motor activity; dynein heavy chain binding; dynein light chain binding
Biological process: cilium movement; determination of left/right symmetry; flagellated sperm motility; outer dynein arm assembly; insulin receptor signaling pathway
Cellular component: cilium; dynein axonemal particle; outer dynein arm; sperm flagellum; cytoskeleton; 9+2 motile cilium; axoneme; centrosome; cytoplasm; manchette; microtubule cytoskeleton; motile cilium
Genetic constraint (gnomAD): Loss-of-function variants: 67 observed, 96.2 expected, observed/expected ratio (o/e) 0.7, 90% interval 0.57 to 0.85. The upper end of that interval is the gene's LOEUF score, 0.85, which puts it in group 3 of 6, group 1 being the genes least tolerant of losing a copy. Missense variants: 839 observed, 909.69 expected, observed/expected ratio (o/e) 0.92, 90% interval 0.87 to 0.98. Synonymous variants: 323 observed, 334.82 expected, observed/expected ratio (o/e) 0.96, 90% interval 0.88 to 1.06.
Homologues: Orthologues: chimpanzee DNAI1 (99% identical), macaque DNAI1 (95% identical), rabbit DNAI1 (89% identical), dog DNAI1 (88% identical), guinea pig DNAI1 (88% identical), mouse Dnai1 (88% identical), pig DNAI1 (88% identical), rat Dnai1 (86% identical), tropical clawed frog dnai1 (65% identical), zebrafish dnai1.2 (56% identical), Drosophila melanogaster CG9313 (44% identical), zebrafish dnai1.1 (41% identical). Paralogues in human: DNAI4 (27% identical), DYNC1I2 (17% identical), DYNC1I1 (16% identical), DNAI3 (16% identical), DYNC2I1 (15% identical), DNAI2 (15% identical), DYNC2I2 (14% identical).
Diseases named in the same sentence as DNAI1 in open-access papers:
DNAI1 is named in the same sentence as 28 diseases in open-access papers, as found by Europe PMC text mining. Sharing a sentence is not in itself a finding about the gene and the disease. The quoted sentences say what the papers report.
primary ciliary dyskinesia (17 papers, 2009 to 2025). A rare, genetically heterogeneous, primarily respiratory disorder characterized by chronic upper and lower respiratory tract disease. "Dynein axonemal intermediate chain 1 protein (DNAI1) plays an essential role in cilia structure and function, while its mutations lead to primary ciliary dyskinesia (PCD)." (PMID 38311768, 2024). "The variant in DNAI1 is heterozygous; however primary ciliary dyskinesia caused by mutations in DNAI1 is inherited in an autosomal recessive manner." (PMID 33574797, 2020). "Recessive mutations in Dynein Axonemal Intermediate chain type 1 (DNAI1) gene have been described in 10% of cases of Primary Ciliary Dyskinesia." (PMID 19300481, 2009). "A study of Polish patients with primary ciliary dyskinesia (PCD) has resulted in the identification of two recurrent alleles, DNAI1 c.1612G>A (p.Ala538Thr) and ZMYND10 c.367delC (p.His123Thrfs*16)." (PMID 39273284, 2024). "The mutation of DNAI1 gene is a part of external power of ciliary organ, and is the second most important genetic cause of primary ciliary dyskinesia (PCD)." (PMID 34488541, 2021). "But the observation that Dic61B is homologous to Axonemal Dynein intermediate chain of various organisms, including DNAI1 of humans implicated in Primary Ciliary Dyskinesia (PCD), associated with infertility due to immotile sperms provided the clue that it might be an axonemal Dic." (PMID 22145020, 2011). "Mutations in the DNAI1 gene, encoding a component of outer dynein arms of the ciliary apparatus, are the second most important genetic cause of primary ciliary dyskinesia (PCD), the genetically heterogeneous recessive disorder with the prevalence of ~1/20,000." (PMID 21143860, 2010). "One patient with VUS in CCDC40 and DNAI1 had Kartagener syndrome, respectively, and one patient with VUS in CCDC40 had a history of congenital heart but no laterality defect." (PMID 37998386, 2023). "DNAI1 anomalies have been previously associated with TGA, while the central pair associated protein SPAG17 has been associated only with Primary Ciliary Dyskinesia (PCD)." (PMID 36140829, 2022). "As an example, DNAH11, DNAH5, DNAI1, and CCDC40 genes have been linked to primary ciliary dyskinesia." (PMID 33574797, 2020). "Furthermore, the strongest interacted genes from our PPI data were primary ciliary dyskinesia-related genes DNAI1, DNAI2, and DNAH5, suggesting the role of cilia in CPAM." (PMID 37165378, 2023). "The first gene described to be responsible for PCD and Kartagener syndrome was DNAI1 gene." (PMID 19300481, 2009). "Genetic mutations (DNAH5, DNAI1, and ZIC3) have been linked to the development of SIT, particularly in association with primary ciliary dyskinesia (PCD)." (PMID 40772152, 2025). "In this regard, we observed situs inversus totalis (Kartagener syndrome) in two patients with VUS in CCDC40 and DNAI1 and female infertility in another patient with VUS in CCDC40, as previously reported by others." (PMID 37998386, 2023). "Interestingly, a cluster formed by 12 elements, including WDR63, DNAH3, DNAI1, TTC18, SPAG17, TTC25, and CCDC113, was found to be a cluster related to primary ciliary dyskinesia and COPI-independent Golgi-to-ER (Cluster 10689, STRING False Discovery Rate: 1.0–12)." (PMID 36140829, 2022).
Infertility (7 papers, 2011 to 2025). "A reduction in the DNAI1 gene might lead to ciliary loss of function, resulting in immotile sperm and ultimately infertility." (PMID 36211460, 2022). "We cannot exclude that heterozygous variants in DNAI1 may cause a milder phenotype characterized only by infertility." (PMID 33574797, 2020). "Main genetic mutations involved in pathology are the DNAI1 and DNAH5 genes result in compromised ciliary motility, leading to a predisposition for recurrent sinopulmonary infections, infertility, and anomalies in left–right body orientation." (PMID 40337424, 2025). "For example, alterations in genes such as SPATA7, DNAH1, DNAI1, and DNAJB11 have been associated with MMAF-related infertility." (PMID 40410177, 2025). "In KS, mutations in the DNAI1 and DNAH5 genes result in impaired ciliary motility, leading to a predisposition for recurrent sinopulmonary infections, infertility, and anomalies in left–right body orientation." (PMID 40337424, 2025). "We found that the structure of the gonads and sperm were greatly deformed, and we identified several promising genes related to spermatogenesis and infertility, such as SPEF2, DNAI1, and TACR3, through RNA-seq." (PMID 36617567, 2023). "Furthermore, we found that fadrozole permanently influenced the differentiation of secondary sexual characteristics and reproductive tissues, and we identified several candidate genes, such as SPEF2, DNAI1, and TACR3, that were related to infertility in sex-reversed chickens." (PMID 36617567, 2023).
male infertility (5 papers, 2020 to 2025). The inability of the male to effect fertilization of an ovum after a specified period of unprotected intercourse. "However, mutations in DNAH5, DNAH11, and DNAI1 also lead to male infertility due to isolated non-syndromic asthenozoospermia." (PMID 36726469, 2022).
situs inversus (4 papers, 2019 to 2023). A congenital condition in which there is complete right-to-left reversal of the position of the major thoracic and abdominal organs (that is, they are arranged in a mirror image of the normal positioning). "A total of 36% of situs inversus cases in our study were associated with the following genes: DNAH5, DNAI1, DNAI2, DNAAF5, and LRRC56." (PMID 37892347, 2023). "Variants in other genes such as DNAL1 (OMIM: 610062), DNAI1 (OMIM: 604366) and DNAH11 (OMIM: 603339), which are coding for dynein compartments, are known to cause situs inversus-like phenotypes." (PMID 30679815, 2019).
asthenozoospermia (3 papers, 2020 to 2025). "Four patients with an extreme (oligo)asthenozoospermia had one homozygous or two heterozygous pathogenic variant(s) in MMAF‐associated genes (CFAP43, CFAP69, DNAI1, and FSIP2)." (PMID 39180390, 2025).
osteosarcoma (3 papers, 2020 to 2023). A usually aggressive malignant bone-forming mesenchymal neoplasm, predominantly affecting adolescents and young adults. "The results showed that the mRNA expression level of four ubiquitin-related genes (CORO6, UBE2L3, FBXL5, DNAI1) was significantly increased in osteosarcoma tissues as compared with adjacent normal tissues." (PMID 36060009, 2022). "Among them, five genes, including CD180, MYC, PROSER2, DNAI1, and FATE1, with significant contribution to the model were selected as the candidate genes in the optimal prognostic risk model of osteosarcoma." (PMID 33082842, 2020). "The expression of ubiquitin-related genes (CORO6, UBE2L3, FBXL5, DNAI1, and DCAF8) showed an obvious significance in normal and osteosarcoma tissues." (PMID 36060009, 2022). "Likewise, DCAF8 lncRNA-associated mRNA, DCAF8, is a ubiquitin-related gene that decreased in osteosarcoma tissues, and together with other ubiquitin-related genes (CORO6, UBE2L3, FBXL5, DNAI1) seem to play a significant role in the clinical outcome of osteosarcoma." (PMID 36831395, 2023).
cystic fibrosis (2 papers, 2020 to 2024). Autosomal recessive disorder caused by pathogenic variants in the CFTR gene (cystic fibrosis transmembrane conductance regulator), which encodes a chloride and bicarbonate channel expressed in epithelial cells, and follow the diagnosis criteria. "Absence of mutations in DNAI1, DNAH5, and CFTR genes ruled out primary ciliary dyskinesia and cystic fibrosis." (PMID 32991486, 2020).
Hydrocephalus (2 papers, 2012 to 2021). Hydrocephalus is an active distension of the ventricular system of the brain resulting from inadequate passage of CSF from its point of production within the cerebral ventricles to its point of absorption into the systemic circulation. "The occurrence of PCD and hydrocephalus has been reported in the past and has been shown to be associated with mutations in various genes (DNAI1, DNAH5, DNAH11, DNAI2, KTU, and RSPH9/4A)." (PMID 33999288, 2021).
behavioral disorders (1 paper, 2021). "Genes linked to congenital and behavioral disorders included dynein axonemal intermediate chain 1, Rho GTPase Activating Protein 36, ATPase Na+/K+ Transporting Subunit Alpha 3 and 5-Hydroxytryptamine Receptor 2C while genes related to fitness effects include genes such as Cysteine-Three-Histidine." (PMID 34209092, 2021).
hepatocellular carcinoma (1 paper, 2017). A malignant tumor that arises from hepatocytes. "Just the variants in DNAI1 and CALD1 have been reported in ExAC very rarely (heterozygote frequency < 0.01%); the DNAI1 variant was found in a hepatocellular carcinoma (COSMIC)." (PMID 29213343, 2017).
Huntington disease (1 paper, 2022). Huntington disease (HD) is a rare neurodegenerative disorder of the central nervous system characterized by unwanted choreatic movements, behavioral and psychiatric disturbances and dementia. "The hub genes in gene set B were DNAI2, DNAI1, DNAH1, DNAH9 and DNALI1, all of which were enriched in Huntington’s disease." (PMID 36577966, 2022).
nasal polyps (1 paper, 2025). "Examples of such additional implications are shown in P179, who had many upper airway infections and nasal polyps as a child and is now diagnosed with PCD due to two heterozygous pathogenic variants in the DNAI1 gene." (PMID 39180390, 2025).
pulmonary fibrosis (1 paper, 2024). Chronic progressive interstitial lung disorder characterized by the replacement of the lung tissue by connective tissue, leading to progressive dyspnea, respiratory failure, or right heart failure. "In particular; due to the structural function in respiratory cilia, roles in vasoconstriction and existing implication in pulmonary fibrosis, DNAI1 and ECE1 respectively, are of great interest." (PMID 39363014, 2024).
sinusitis (1 paper, 2025). An acute or chronic inflammatory process affecting the mucous membranes of any sinus cavity. "For example, treatment of Dnai1flox/flox/CreER+ mice with different doses of tamoxifen showed that the rate of MCC was correlated with the level of intact genomic Dnai1, where animals with at least 20% of normal Dnai1 levels exhibited MCC with no mucus accumulation and no sinusitis phenotype." (PMID 40963409, 2025).
infection (67 papers, 2009 to 2026). The state of being infected such as from the introduction of a foreign agent such as serum, vaccine, antigenic substance or organism. "Consequently, we pursued the infection experiments on DNAI1-mutated HAECs with the Kozak modified/DNAI1 conserved pair of vectors (with and without HA tag)." (PMID 19300481, 2009). "Extended culture of HRV-infected epithelium was accompanied by almost complete normalization of mRNAs deregulated during the acute infection phase, including FOXJ1 and DNAI1, which suggests a quick restoring of ciliogenesis." (PMID 34140575, 2021).
cancer (2 papers, 2020 to 2025). A tumor composed of atypical neoplastic, often pleomorphic cells that invade other tissues. "The main pathways of methylome biomarkers were associated with calcium signalling (CACNA1E, RYR2, RYR3), cancer pathways (DCC, RASSF1, WNT1, CTNNA2), multiple neurodegenerative diseases (WNT1, DNAI1, RYR2, RYR3), immune system disorders and cell adhesion (HLA-DRA, HLA-DRB1, HLA-DRB5)." (PMID 40524349, 2025). "In addition to DNAI1, another three genes, MYC, PROSER2, and FATE1, have been reported to be associated with several cancers." (PMID 33082842, 2020).
cardiac disease (1 paper, 2016). "Among these 4 genes, TTN was the most likely cardiac disease associated gene while lack of evidence for NPHP3, DNAI1, and MUC5B genes existed." (PMID 28018021, 2016).
DNAI1 also shares sentences with these, for which no sentence is quoted: bacterial infection (4 papers); tumor (2); virus infection (2); asthma (1); cone-rod dystrophies (1); familial intrahepatic cholestasis (1); female infertility (1); Fusarium infection (1); immune system disorder (1); Kartagener Syndrome (1); Situs inversus totalis (1).